WWTR1 (WW domain containing transcription regulator 1)
Diseases named in the same sentence as WWTR1 in open-access papers (continued):
Sharing a sentence is not in itself a finding about the gene and the disease.
mesothelioma (1 paper, 2024). A usually malignant and aggressive neoplasm of the mesothelium which is often associated with exposure to asbestos. "A number of selective inhibitors of the TEAD family members are in development and have been shown to disrupt YAP1/WWTR1/TEAD-dependent transcription, affect the viability of NF2 mutant mesothelioma models, and to enhance the efficacy of EGFR inhibitors in EGFR mutant lung cancer." (PMID 38658677, 2024).
multiple myeloma (1 paper, 2021). "In multiple myeloma, the WWTR1 promoter is hypermethylated and thus silenced; re-expression of TAZ leads to apoptosis via repression of MYC and its targets." (PMID 33582842, 2021).
pulmonary hypertension (1 paper, 2021). Increased pressure within the pulmonary circulation due to lung or heart disorder. "YAP is a transcriptional regulator that, together with WW domain-containing transcription regulator 1 (WWTR1 or TAZ), contributes to PASMC proliferation and subsequent pulmonary hypertension under hypoxic conditions through inhibition of cyclooxygenase 2 (COX2) activity." (PMID 34434114, 2021).
Renal cyst (1 paper, 2021). A fluid filled sac in the kidney. "Significantly fewer cilia per cell were observed in the renal cysts of Wwtr1 OE fish compared to those of WT controls." (PMID 34545930, 2021). "Overall, our analyses revealed roles of Stk3 and Wwtr1 in renal cyst formation." (PMID 34545930, 2021).
renal cystic dysplasia (1 paper, 2015). "The expression of GLIS3 and WW domain containing transcription regulator 1 (WWTR1) overlaps in the kidney, and mutations in both genes result in renal cystic dysplasia with a high glomerular cystic load." (PMID 26259131, 2015).
rhabdomyosarcoma (1 paper, 2016). A rare aggressive malignant mesenchymal neoplasm arising from skeletal muscle. "Comparison with expression data showed that the expression level of the WWTR1 gene correlates with the copy number of its chromosomal locus, with a Pearson correlation coefficient (r) = 0.31 for fusion gene‐negative rhabdomyosarcoma (p = 0.046)." (PMID 27184927, 2016). "Re‐analysis of a previously publicly available dataset 33 revealed copy number gains of the region of Chromosome 3 that incorporates the WWTR1 locus (chromosome 3q24‐q24) in 12% (five of 43) of human fusion gene‐negative rhabdomyosarcomas, but not in fusion gene‐positive ARMS." (PMID 27184927, 2016).
skin cancer (1 paper, 2021). "WWTR1, as component of the Hippo pathway, has been already associated with the regulation of the complex machinery governing cell adhesion and perception of mechanical forces, as well as to the development of some skin cancer types." (PMID 33890134, 2021).
steatosis (1 paper, 2023). Increased lipid within the cytoplasm of cells. "Similarly, LXR activation in hepatocytes suppressed the transactivation of a subset of NASH-promoting genes by destabilizing the TAZ (WWTR1) protein level, halting the progression from steatosis to steatohepatitis." (PMID 37174692, 2023).
thyroid cancer (1 paper, 2025). "Gene expression analysis in a cohort of patients with thyroid cancer showed a significant positive correlation between WWTR1 and ATF4 (Spearman correlation r=0.33, p<0.001)." (PMID 40667288, 2025). "The analysis of WWTR1 expression in different histological types of thyroid cancer revealed a higher expression in human ATC tumors compared to differentiated thyroid cancer (PTC) and normal tissue." (PMID 40667288, 2025).
ZIKV infection (1 paper, 2021). "Overexpression of RhoV and WWTR1 significantly enhanced ZIKV infection by up to 2.6-fold at 12 h.p.i., an effect which persisted up to 18–24 h.p.i. for RhoV (clone 2) and WWTR1 (clone 15)." (PMID 34834920, 2021). "Overexpression of either RhoV or WWTR1 is expected to increase ZIKV infection or ZIKV-induced cell death." (PMID 34834920, 2021). "We identified Ras homolog family member V (RhoV) and WW domain-containing transcription regulator 1 (WWTR1) as proviral factors, and found them to play important roles during early ZIKV infection in A549 cells." (PMID 34834920, 2021). "In this study, we identified RhoV and WWTR1 as candidate host proviral factors for ZIKV infection by performing a genome-wide CRISPR activation screen, which has the advantage of upregulating all gene isoforms from their endogenous promoter contexts." (PMID 34834920, 2021). "To investigate the effects of RhoV and WWTR1 on ZIKV infection, we treated these inducible cell lines with Dox and infected them with ZIKV." (PMID 34834920, 2021).
cancer (73 papers, 2012 to 2025). A tumor composed of atypical neoplastic, often pleomorphic cells that invade other tissues. "The mechanism underlying WWTR1-promoted tumor metastasis has been investigated in varies types of cancer cell lines and with a metastatic mouse model." (PMID 30976198, 2019). "WWTR1, downstream effectors of Hippo pathways, was associated with worse prognostic outcome in various cancers." (PMID 28968955, 2017). "However, overexpression of WWTR1 has been associated with enhanced cancer growth and poor prognosis in GC." (PMID 39941831, 2025). "As WWTR1 is known to have important roles in the context of cancer 26, 47, 48, we next performed loss- and gain-of-function experiments in order to ascertain as to whether WWTR1 contributed to the anti-leukemic activity of miR-550-1." (PMID 33061801, 2020). "This interesting observation led us to postulate that OSCC cancers with a gene expression signature associated with WWTR1 dependency might be more vulnerable to checkpoint blockade." (PMID 32990596, 2020). "In the majority of cancers, WWTR1 and YAP1 have been reported to lack mutations." (PMID 30167083, 2018). "The potent antiproliferative effect explains why YAP and its paralog WWTR1/TAZ are silenced in YAPoff cancers." (PMID 39172021, 2024). "It mentions that factors like Cadherin 1 and integrin subunits α6 and β4 protect against ferroptosis, while the activation of the Hippo pathway (involving YAP1 and WWTR1/TAZ) promotes ferroptosis in cancer cells." (PMID 38369484, 2024). "We further examined the expression levels of 22 YAP1/WWTR1 signature genes identified in cancers by the previous study." (PMID 38624208, 2024). "Prior work has shown that expression of YAP1 or WWTR1 is detrimental to the viability of NEhi cancer cell lines." (PMID 36719743, 2023). "In these cancers, YAP1 and WWTR1 expression is associated with increased drug resistance, metastasis, and poor outcomes." (PMID 36719743, 2023). "SCCs of the lung, oesophagus and head and neck display the highest levels of YAP1 or WWTR1 gene amplifications across multiple cancer types, often in a mutually exclusive manner." (PMID 35913427, 2022). "For the Hippo pathway, apart from YAP1 that showed upregulation in carcinoma cell lines (H314, H157, H413 and SqCC/Y1), WWTR1/TAZ was also overexpressed in H314, H413 and SqCC/Y1 plus D17‐TERT dysplasia line." (PMID 35000271, 2022). "WWTR1 is a downstream transcriptional coactivator of the Hippo pathway and has been reported to be overexpressed in various human cancers, which correlated to cancer aggressiveness by promoting malignant cell proliferation and inhibiting apoptosis." (PMID 34437475, 2021). "The transcriptional coactivator with PDZ-binding motif (TAZ) (WWTR1) induces epithelial–mesenchymal transition and enhances drug resistance in multiple cancers." (PMID 34022224, 2021). "YAP (Yap1) and TAZ (Wwtr1) are transcriptional co-activators and downstream effectors of the Hippo pathway, which play crucial roles in organ size control and cancer pathogenesis." (PMID 32992050, 2021). "In human cancers, the dysregulation of the Hippo pathway and WWTR1 gene amplification lead to TAZ hyperactivation." (PMID 34022224, 2021). "Given that YAP1 and WWTR1 share about 60% homology, it cannot be excluded that we co-detected WWTR1 in addition to YAP1 at least in cancers with very high WWTR1 expression levels." (PMID 32488048, 2020). "On the other hand, tyrosine 357-phosphorylated YAP binds and activates a complex between β-catenin and the transcription factor TBX5 in the nucleus of β-catenin driven cancers to activate a number of anti-apoptotic genes, including WWTR1." (PMID 32326412, 2020). "WWTR1 is involved in multiple cancer cell signaling pathways, including WNT/CTNN, Ga12/Ga13/Rho, mevalonate/geranylgeranylation, mTOR, and fluid shear signaling pathways, that regulate cell proliferation, EMT, angiogenesis, drug resistance of tumors." (PMID 30976198, 2019).
cancer (continued). "For example, the cancer-related gene WWTR1 was coregulated by H19 and lncRNA TP73-AS1 through four different miRNAs." (PMID 31164794, 2019). "Additional genetic alterations of Hippo pathway genes in cancer have also been reported, for instance, WWTR1-CAMTA and YAP1-TFE3 fusion are found in epithelioid hemangioma." (PMID 31072060, 2019). "TAZ, the product of the WWTR1 gene, is a downstream effector of the Hippo pathway that, when inappropriately active, can drive the development and progression of numerous cancers." (PMID 29996478, 2018). "Our results indicate that epigenetic modifier JMJD1a is a mechanosensitive regulator of the transcription of many genes, including YAP and TAZ (WWTR1) and of cancer cell proliferation." (PMID 27488962, 2016). "WWTR1 (also known as TAZ) is a well-described oncogenic transcriptional co-activator in many cancers including breast, liver, colon, thyroid, and lung." (PMID 27602958, 2016). "Nonetheless, TAZ, like YAP, has been associated with cancer 17, 18, suggesting that both YAP1 and WWTR1 can act as oncogenes." (PMID 27184927, 2016). "TAZ, also known as WWTR1 (transcriptional regulator 1 containing the WW structural domain), has been identified to exhibit elevated expression and activity in a range of human cancers." (PMID 40990019, 2025). "Indeed, in various cancers, increased YAP/TAZ levels have been observed because of mutations in MST1/2 and LATS1/2 as well as gene amplification of YAP1 and WWTR1, which encode YAP and TAZ." (PMID 39527559, 2024). "In addition, both genetic and pharmacologic inhibition of YAP1/WWTR1/TEAD-dependent transcription re-sensitizes resistant cells to osimertinib as well as preventing the future emergence of persister cancer cells." (PMID 38658677, 2024). "In addition, H3K4me3 enrichment was also decreased at the promoters of Myc, WW domain-containing transcription regulator protein 1 (Wwtr1) and neuropilin 1 (Nrp1), which participate in cancer metastasis, after GATM knockdown." (PMID 37370109, 2023). "In addition, WWTR1 can participate in many cancer cell signaling pathways, such WNT, mTOR and EMT signaling pathway." (PMID 37091799, 2023). "We previously confirmed that WWTR1 silencing compromises the cell viability in these cancer cells." (PMID 34022224, 2021). "Interestingly, WWTR1 and YAP1_PS127 both belong to the Hippo signaling pathway, and they are frequently hyperactivated in cancer." (PMID 33014785, 2020). "Furthermore, YAP1 or WWTR1 amplifications occur in approximately 19% of HNSCC (YAP1–5.5%, WWTR1–14.3%), which puts it among the top five cancers with the highest amplification of these genes amongst 33 cancer types." (PMID 32990596, 2020). "The roles of the Hippo signaling pathway and its effectors YAP1 and WWTR1 in cancer immunity remains unclear." (PMID 32990596, 2020). "The oncogene Yes-associated protein (YAP) and its paralogue Transcriptional Co-Activator With PDZ-binding Motif (TAZ or WWTR1) have been considered as attractive pharmacological targets, as they are highly activated in many forms of cancers and contribute to tumor growth and invasion." (PMID 33614496, 2020). "Disruption of the Hippo signaling, or abnormal activation of Yes-associated protein (YAP; also known as YAP1) and transcriptional co-activator with PDZ-binding motif (TAZ; also known as WWTR1) leads to a number of diseases including inflammation, fibrosis and cancer." (PMID 30700007, 2019). "We will follow the hypothesis and further determine the mechanism by which the WWTR1/CYR61 signaling axis promotes cancer cell migration, invasion and metastasis in future studies." (PMID 30976198, 2019). "It is noticed that WWTR1 enhances cancer cell drug-resistance that may sustain cancer cell survival in bloodstream and increase the cancer cell deposition in the remote metastatic tissue." (PMID 30976198, 2019).
cancer (continued). "Notably, all three YAP1/WWTR1 compensable cell lines (BICR10, HSC-2 and HSC-4) harbor PIK3CA mutation, and that alterations in the PI3K signaling pathway have been linked to multiple metabolic dysregulations in cancer." (PMID 32990596, 2020). "The specific effect of Mith A on WWTR1 mRNA expression was also observed in the HPV18 + SW756 and related HPV45 + MS751 cancer cell lines, arguing against a cell line-specific effect." (PMID 38987584, 2024). "Beyond that, tumor stiffness impacts cancer cells, CSCs, and stromal cells through activation and nuclear translocation of the transcriptional activators YAP1 and WW domain-containing transcription regulator 1 (WWDR1) (TAZ) (Hippo pathway)." (PMID 38397421, 2024). "Opposite expression and pro- or anti-cancer function of YAP and its paralog TAZ/WWTR1 stratify cancers into binary YAPon and YAPoff classes." (PMID 39172021, 2024). "In a short-term assay, combining osimertinib with the K-975 TEAD inhibitor (at a single dose shown to disrupt YAP1/WWTR1 and TEAD binding) resulted in a dose-dependent and significant decrease in persister cancer cells." (PMID 38658677, 2024). "Expression of YAP1 and WWTR1 in YAP1- and WWTR1-silenced cancers, including NEhi SCLC, can suppress proliferation." (PMID 36719743, 2023). "In general, other YAP1- and WWTR1-silenced cancers typically grow in suspension, while YAP1- and WWTR1-expressing cancers grow adherently." (PMID 36719743, 2023). "Consistent with links between the blue module and cancer, we find that many blue module hub genes, such as Moesin (MSN), YAP1, TEAD1, and WWTR1 are well known for their role in cancer and mediate the EMT." (PMID 36879821, 2023). "We observed decreased expression of YAP1, WWTR1, CTGF and CYR61 in Cancer Luminal type A/B cells when compared with normal mature luminal cells." (PMID 35217640, 2022). "The WWTR1–ASNS network, ATF4–ASNS network, and DDIT3–ASNS network are reported to inhibit the proliferation and tumor formation of cancer cells." (PMID 35625787, 2022). "Instead of point mutations, gene fusions are the most common genetic alterations of TAZ(WWTR1) and YAP in cancer." (PMID 33913810, 2021). "As an important component of the Hippo pathway, WW domain-containing transcription regulator 1 (TAZ), is a transcriptional coactivator that is responsible for the progression of various types of cancers." (PMID 34736474, 2021). "WW domain-containing transcription regulator 1 (TAZ) is a downstream nuclear effector in the Hippo pathway that induces the proliferation and inhibits the apoptosis of cancer cells." (PMID 34736474, 2021). "Cancer patients with high CCN1 expression have poor survival outcomes and positive correlation with ITGAV and ITGB3 and high YAP/WWTR1." (PMID 31429823, 2019). "Distinct from typical oncogenes, YAP1 and WWTR1 do not independently initiate spontaneous cancer development, though they are indispensable for tumor progression." (PMID 40919137, 2025). "The YAP1:TFE3-fused gene and WWTR1(TAZ)-CAMTA1 gene fusions are characteristic of haemangioendothelioma, whereas the presence of FUS:DDIT3 or EWSR1:DDIT3 genes is pathognomonic in myxoid liposarcoma (MLPS), a malignant tumour, recapitulating lipogenesis." (PMID 37681936, 2023). "WWTR1 and TGIF1 were also reported to be involved in cancer development in various cancer types." (PMID 36157222, 2022). "Furthermore, H19 regulated many other cancer-related genes in this network, such as AKT3, CSF1, MET, COL1A1, COL5A1, WWTR1, EPHB4, and TMPRSS3." (PMID 31164794, 2019). "The two gene fusions are the only consistent genetic alterations of WWTR1 and YAP1 in a cancer." (PMID 27129148, 2016). "Because YAP1 and WWTR1 are located at the crossroads of adhesion, GPCR, RTK and stem-cell signaling network, cancer genomics of the FAT signaling cascades could be applied for diagnostics, prognostics and therapeutics in the era of personalized medicine." (PMID 23076869, 2012).
cancer (continued). "Since the initial discovery of this fusion, the YAP1–TFE3 fusion has also been identified in the clear-cell stromal tumor of the lung and in a case of cutaneous low-grade fibromyxoid neoplasm; no additional cancers have been identified that harbor the WWTR1–CAMTA1 fusion." (PMID 35740643, 2022). "WWTR1 gene expression showed significant negative correlation with its dependency in these 273 cancer cell lines (Pearson R = −0.570, p-value=3e-25) and showed non-significant negative correlation among our 21 OSCC lines screened (Pearson R = −0.354, p-value=0.116)." (PMID 32990596, 2020). "The lack of dependency on either YAP1 or WWTR1 in the non-dependent lines is intriguing, given the importance of these genes in most OSCC cancer cells." (PMID 32990596, 2020). "This revealed that WWTR1 and YAP1 (not shown) were highly expressed in most cancer cell lines, with the exception of low expression in blood cancers." (PMID 27184927, 2016).